MARCHF7 (membrane associated ring-CH-type finger 7)
Description:
E3 ubiquitin-protein ligase which may specifically enhance the E2 activity of HIP2. E3 ubiquitin ligases accept ubiquitin from an E2 ubiquitin-conjugating enzyme in the form of a thioester and then directly transfer the ubiquitin to targeted substrates. May be involved in T-cell proliferation by regulating LIF secretion (By similarity). May play a role in lysosome homeostasis. Promotes 'Lys-6', 'Lys-11' and 'Lys-63'-linked mixed polyubiquitination on ATG14 leading to the inhibition of autophagy by impairing the interaction between ATG14 and STX7. Participates in the dopamine-mediated negative regulation of the NLRP3 inflammasome by promoting its ubiquitination and subsequent degradation.
Synonyms: MARCH-VII; AXOT; MARCH7; RNF177; AXO
Tractability: Antibody: its Gene Ontology location is reachable by antibodies, with high confidence. PROTAC: ubiquitination databases record sites on it.
Gene: Protein-coding gene on chromosome 2 (159,712,001 to 159,771,027, forward strand). Ensembl gene ENSG00000136536.
Subcellular location: Cytoplasm
Subcellular location (Human Protein Atlas): Cytosol; Plasma membrane; Basal body
Gene Ontology:
Molecular function: MDM2/MDM4 family protein binding; protein binding; ubiquitin conjugating enzyme binding; ubiquitin protein ligase activity; ubiquitin binding; enzyme binding; zinc ion binding
Biological process: negative regulation of cilium assembly; negative regulation of proteasomal protein catabolic process; negative regulation of protein autoubiquitination; positive regulation of cell population proliferation; positive regulation of protein polyubiquitination; protein monoubiquitination; protein stabilization; protein autoubiquitination; protein ubiquitination
Cellular component: centrosome; cytoplasm; cytosol; nucleus; plasma membrane
Genetic constraint (gnomAD): Loss-of-function variants: 12 observed, 50.07 expected, observed/expected ratio (o/e) 0.24, 90% interval 0.15 to 0.39. The upper end of that interval is the gene's LOEUF score, 0.39, which puts it in group 1 of 6, group 1 being the genes least tolerant of losing a copy. Missense variants: 619 observed, 660.85 expected, observed/expected ratio (o/e) 0.94, 90% interval 0.88 to 1. Synonymous variants: 240 observed, 240.42 expected, observed/expected ratio (o/e) 1, 90% interval 0.9 to 1.11.
Homologues: Orthologues: macaque MARCHF7 (99% identical), chimpanzee MARCHF7 (93% identical), dog MARCHF7 (92% identical), pig MARCHF7 (90% identical), rabbit MARCHF7 (90% identical), rat Marchf7 (86% identical), mouse Marchf7 (85% identical), guinea pig MARCHF7 (82% identical), tropical clawed frog marchf7 (52% identical), zebrafish marchf7 (42% identical). Paralogues in human: MARCHF10 (24% identical).
Diseases named in the same sentence as MARCHF7 in open-access papers:
MARCHF7 is named in the same sentence as 18 diseases in open-access papers, as found by Europe PMC text mining. Sharing a sentence is not in itself a finding about the gene and the disease. The quoted sentences say what the papers report.
osteosarcoma (1 paper, 2026). A usually aggressive malignant bone-forming mesenchymal neoplasm, predominantly affecting adolescents and young adults. "On the other hand, a previous study reported that MARCHF7 mediates the ubiquitination of ATG14, thereby reducing the number of aggresome-like structures in osteosarcoma U2OS cells." (PMID 41267209, 2026).
tumor (7 papers, 2015 to 2025). "MARCHF7, a RING E3 ligase, plays a role in T cell proliferation, neuronal development, inflammasome regulation, and tumor progression." (PMID 40358464, 2025).
cancer (6 papers, 2015 to 2024). A tumor composed of atypical neoplastic, often pleomorphic cells that invade other tissues. "Liu and colleagues demonstrated that Membrane Associated Ring-CH-Type Finger 7 (MARCH7) is a key protein in EMT and cancer stemness." (PMID 31752447, 2019).
infection (2 papers, 2015 to 2025). The state of being infected such as from the introduction of a foreign agent such as serum, vaccine, antigenic substance or organism. "Histopathological analysis at 5 days post-infection showed that lungs from UBR5- or MARCHF7-treated mice exhibited reduced alveolar contraction and pulmonary edema compared to the severe lesions observed in control mice." (PMID 40358464, 2025). "To investigate the impact of SARS-CoV-2 infection on UBR5 and MARCHF7 expression, we analyzed their mRNA and protein levels following infection with the IME-BJ01 and Omicron strains at varying MOIs using RT-qPCR and IB." (PMID 40358464, 2025). "MARCHF7 expression decreased consistently with increasing viral titers, whereas UBR5 levels initially rose at low titers before declining as infection progressed." (PMID 40358464, 2025).
MARCHF7 also shares sentences with these, for which no sentence is quoted: ovarian carcinoma (8 papers); breast carcinoma (2); endometrial cancer (2); ovarian tumor (2); bladder cancer (1); bladder tumors (1); COVID-19 (1); endometrioid adenocarcinoma (1); esophageal squamous cell carcinoma (1); gastric cancer (1); lysosomal disorders (1); mucinous adenocarcinoma (1); serous adenocarcinoma (1); serous papillary adenocarcinoma (1).